XPOT (exportin for tRNA)
Description:
Mediates the nuclear export of aminoacylated tRNAs. In the nucleus binds to tRNA and to the GTPase Ran in its active GTP-bound form. Docking of this trimeric complex to the nuclear pore complex (NPC) is mediated through binding to nucleoporins. Upon transit of a nuclear export complex into the cytoplasm, disassembling of the complex and hydrolysis of Ran-GTP to Ran-GDP (induced by RANBP1 and RANGAP1, respectively) cause release of the tRNA from the export receptor. XPOT then return to the nuclear compartment and mediate another round of transport. The directionality of nuclear export is thought to be conferred by an asymmetric distribution of the GTP- and GDP-bound forms of Ran between the cytoplasm and nucleus.
Synonyms: XPO3
Tractability: PROTAC: ubiquitination databases record sites on it; its protein half-life has been measured.
Gene: Protein-coding gene on chromosome 12 (64,404,168 to 64,451,129, forward strand). Ensembl gene ENSG00000184575.
Subcellular location: Nucleus; Cytoplasm
Subcellular location (Human Protein Atlas): Nucleoplasm; Cytosol
Pathways (Reactome):
Metabolism of RNA: tRNA processing in the nucleus
Gene Ontology:
Molecular function: protein binding; tRNA binding; small GTPase binding
Biological process: tRNA export from nucleus; tRNA re-export from nucleus; intercellular transport; intracellular protein transport; nucleocytoplasmic transport
Cellular component: cytoplasm; cytosol; nuclear pore; nucleoplasm; nuclear matrix; nucleus
Genetic constraint (gnomAD): Loss-of-function variants: 25 observed, 106.2 expected, observed/expected ratio (o/e) 0.24, 90% interval 0.17 to 0.33. The upper end of that interval is the gene's LOEUF score, 0.33, which puts it in group 1 of 6, group 1 being the genes least tolerant of losing a copy. Missense variants: 765 observed, 1,057.7 expected, observed/expected ratio (o/e) 0.72, 90% interval 0.68 to 0.77. Synonymous variants: 308 observed, 372.52 expected, observed/expected ratio (o/e) 0.83, 90% interval 0.75 to 0.91.
Homologues: Orthologues: chimpanzee XPOT (100% identical), macaque XPOT (99% identical), pig XPOT (99% identical), rabbit XPOT (99% identical), dog XPOT (99% identical), guinea pig XPOT (97% identical), rat Xpot (96% identical), mouse Xpot (95% identical), tropical clawed frog xpot (88% identical), zebrafish xpot (78% identical), Caenorhabditis elegans xpo-3 (26% identical).
Diseases named in the same sentence as XPOT in open-access papers:
XPOT is named in the same sentence as 11 diseases in open-access papers, as found by Europe PMC text mining. Sharing a sentence is not in itself a finding about the gene and the disease. The quoted sentences say what the papers report.
breast carcinoma (3 papers, 2019 to 2023). "Here, we found that XPOT (Exportin-T), a nuclear export protein receptor of tRNAs, is associated with poor prognosis in breast cancer and directly orchestrates the nuclear export of a subset of tRNAs, subsequently promoting protein synthesis and proliferation of human TNBC cells." (PMID 37928256, 2023). "The association of the six top-ranked karyopherins (KPNA2, XPOT, CSEL1, KPNA1, KPNA4, and TNPO1) in the breast cancer datasets from Oncomine was analyzed using a Kaplan-Meier Plotter." (PMID 37928256, 2023). "High XPOT expression predicted worse overall survival in breast cancer, especially in TNBC." (PMID 37928256, 2023). "XPOT was also found to be increased and strongly related to worse OS in breast cancer." (PMID 31371628, 2019). "Significant up-regulation of XPOT (also named XPOT) was found in liver and breast cancers." (PMID 31371628, 2019). "However, the role and underlying mechanisms of XPOT in breast cancer, especially TNBC, have not been explored." (PMID 37928256, 2023).
hepatocellular carcinoma (2 papers, 2021 to 2023). A malignant tumor that arises from hepatocytes. "While several studies have revealed XPOT overexpression in mesothelioma, leukemia HL-60 cells, and hepatocellular carcinoma 20-23, the exact molecular mechanisms of XPOT in these tumors remain elusive, especially whether and how XPOT modulates tumor progression through tRNA nuclear export." (PMID 37928256, 2023).
lung carcinoma (2 papers, 2021 to 2022). "It is worthwhile to determine crosstalk and functional roles between METTL1, CTU2, and XPOT in human cancer, notably lung cancer." (PMID 34285249, 2021).
liver cancer (1 paper, 2019). An epithelial or non-epithelial malignant neoplasm that arises from the liver. "High expression of XPOT in 95 liver cancer tissues predicted a worse prognosis." (PMID 31371628, 2019).
ovarian carcinoma (1 paper, 2025). A malignant neoplasm originating from the surface ovarian epithelium. "Note of worth, four genes (IPO9, KPNA2, TNPO3, and XPOT) and one gene (KPNA5) were consistently significantly up‐ and down‐regulated in ovarian cancer, respectively." (PMID 40145330, 2025).
triple-negative breast carcinoma (1 paper, 2025). An invasive breast carcinoma which is negative for expression of estrogen receptor (ER), progesterone receptor (PR), and human epidermal growth factor receptor 2 (HER2). "Knockdown of human XPOT (exportin for tRNA) increased nuclear tRNA-Glu-TTC-1 in human triple-negative breast cancer (TNBC) cell lines." (PMID 40559619, 2025).
cancer (7 papers, 2019 to 2025). A tumor composed of atypical neoplastic, often pleomorphic cells that invade other tissues. "XPOT was found to be the most obviously upregulated karyopherin transport receptor among the 15 cancers." (PMID 37928256, 2023). "Eight proteins (C-reactive protein, AGRN, XPOT, LDHA, C1QC, ORM1, ANGPTL4, and prostaglandin D2 synthase [PTGDS]) exhibited a continuously upward or downward trend in three or more cancer types." (PMID 39884577, 2025). "Using two-box analysis of The Cancer Genome Atlas (TCGA) and Genotype-Tissue Expression (GTEx) databases, we compared the expression levels of XPO, including XPO1, CSE1L, XPOT, XPO5, and XPO6, in each tumor and normal tissue." (PMID 39882192, 2025). "Through analysis of The Cancer Genome Atlas (TCGA) dataset, the Gene Expression Omnibus (GEO) dataset (GSE13650), and our Renji Hospital cohort, we found that the expression of XPOT mRNA in TNBC tissues was much higher than that in normal tissues." (PMID 37928256, 2023). "Other nuclear exportins, such as XPOT (XPO3), XPO4 and XPO5, have been found to promote or suppress cancers, respectively." (PMID 37243787, 2023). "Furthermore, in this study, we also revealed that two tRNA regulators, CTU2 and XPOT, may be functionally interconnected with METTL1 in cancer." (PMID 34285249, 2021). "Furthermore, functional annotation and pathway analysis of METTL1-associated proteins revealed that, in addition to METTL1 cofactor WDR4, two tRNA regulators, CTU2 and XPOT, may be functionally interconnected with METTL1 in human cancer." (PMID 34285249, 2021). "Likewise, XPOT mRNA levels increased 2.245-fold (Roessler liver dataset, P=8.41e-63) and 1.763-fold (Chen liver dataset, P=4.01e-14) but decreased −2.122-fold in HCC cancer tissues in another HCC dataset (Mas liver dataset, P=4.32e-07)." (PMID 31371628, 2019).
tumor (6 papers, 2019 to 2025). "High XPOT expression was also associated with more aggressive biological characteristics such as larger tumor size (P=0.019), more lymph node metastasis (P=0.014), and higher histological grade (P=0.034)." (PMID 37928256, 2023). "The knockdown efficiency of Lenti-shXPOT-transfected MDA-MB-231 and MDA-MB-468 cells was demonstrated by western blotting, which revealed that XPOT knockdown prominently inhibited tumor growth in the xenograft tumor model established with MDA-MB-468 cells." (PMID 37928256, 2023). "Noticeably, the mRNA expression levels of CSE1L and XPOT/6 were highest in tumor pathological grade 4, while the highest mRNA expression levels of XPO1/4/5/7 were found in grade 3." (PMID 31371628, 2019). "A study revealed XPOT upregulation in HCC tumour tissues, poor outcome for patients with the high expression of the protein and association of XPOT expression with expression of molecules that regulate the cell cycle (i.e. several cyclins and cyclin-dependent kinases) in HCC cells." (PMID 33541355, 2021). "Further evidence suggested that XPOT might affect tumor progression via the cell cycle and ubiquitin-mediated proteolysis." (PMID 31371628, 2019). "XPOT, a member of RAN-GTPase exportin family, which mediates export of tRNA from the nucleus to the cytoplasm, promotes tumor proliferation and invasion in liver cancer." (PMID 34285249, 2021).
XPOT also shares sentences with these, for which no sentence is quoted: leukemia (1 paper); mesothelioma (1); serous ovarian carcinomas (1).